KLHDC9 (kelch domain containing 9)
Synonyms: KARCA1
Tractability: No criterion of Open Targets' tractability assessment is met for any kind of drug.
Gene: Protein-coding gene on chromosome 1 (161,098,361 to 161,100,346, forward strand). Ensembl gene ENSG00000162755.
Subcellular location (Human Protein Atlas): Mitotic chromosome; Nucleoli; Nucleoli rim; Nucleoplasm
Gene Ontology:
Molecular function: cyclin binding; protein binding
Genetic constraint (gnomAD): Loss-of-function variants: 26 observed, 30.3 expected, observed/expected ratio (o/e) 0.86, 90% interval 0.63 to 1.19. The upper end of that interval is the gene's LOEUF score, 1.19, which puts it in group 5 of 6, group 1 being the genes least tolerant of losing a copy. Missense variants: 437 observed, 454.78 expected, observed/expected ratio (o/e) 0.96, 90% interval 0.89 to 1.04. Synonymous variants: 176 observed, 174.78 expected, observed/expected ratio (o/e) 1.01, 90% interval 0.89 to 1.14.
Homologues: Orthologues: macaque KLHDC9 (97% identical), rabbit KLHDC9 (86% identical), pig KLHDC9 (85% identical), mouse Klhdc9 (84% identical), rat Klhdc9 (83% identical), guinea pig KLHDC9 (82% identical), dog KLHDC9 (82% identical), chimpanzee KLHDC9 (69% identical), tropical clawed frog klhdc9 (52% identical), zebrafish hcfc1b (19% identical), zebrafish hcfc1a (18% identical), Drosophila melanogaster Hcf (18% identical), and 2 more. Paralogues in human: KLHDC4 (21% identical), LZTR1 (20% identical), RABEPK (20% identical), HCFC1 (18% identical), HCFC2 (18% identical), KLHDC10 (17% identical), KLHDC3 (17% identical), KLHDC1 (17% identical), KLHDC2 (16% identical), FBXO42 (15% identical).
Diseases named in the same sentence as KLHDC9 in open-access papers:
KLHDC9 is named in the same sentence as 2 diseases in open-access papers, as found by Europe PMC text mining. Sharing a sentence is not in itself a finding about the gene and the disease. The quoted sentences say what the papers report.
breast carcinoma (2 papers, 2017 to 2025). "We further analyze two independent breast cancer datasets and find that specific isoforms of IGF2BP2, NECTIN4, ITGB6, and KLHDC9 are significantly associated with AZD6244, lapatinib, erlotinib, and paclitaxel, respectively." (PMID 29066719, 2017). "We found that expression of the ENST00000490724 isoform of the kelch domain-containing 9 (KLHDC9) gene is associated with lack of sensitivity to paclitaxel in breast cancer cell lines." (PMID 29066719, 2017).
KLHDC9 also shares sentences with these, for which no sentence is quoted: lung adenocarcinoma (1 paper).